SPA17 (sperm autoantigenic protein 17)
Diseases named in the same sentence as SPA17 in open-access papers (continued):
Sharing a sentence is not in itself a finding about the gene and the disease.
tumor (7 papers, 2016 to 2025). "Further multivariate analysis showed SPA17 and tumor size were independent factors associated with overall survival." (PMID 31417875, 2019). "Our results reveal that SPA17 was abnormally expressed in cancer tissues, and this expression pattern could be associated with immune cell infiltrations in tumor microenvironments." (PMID 35592314, 2022). "In most tumors, SPA17was positively associated with the infiltration of MDSC, CD4+ T cells, progenitors of lymphoid, and CD8+ T cells, suggesting that SPA17 was likely to affect tumor development and prognosis by impacting the tumor microenvironment." (PMID 35592314, 2022). "It has been reported that the SPA17 expression is limited in adult somatic tissues and re-expressed in tumor tissues." (PMID 35592314, 2022). "The immunofluorescence (IF) images of the cancer cells showed that SPA17 protein was mainly localized in the vesicles of the A-431 and U251 tumor cell lines, according to the HPA database." (PMID 35592314, 2022). "Our results provide vital clues for future research on the potential role of SPA17 in tumor immunity and immunotherapy." (PMID 35592314, 2022). "The abnormal expression of SPA17 was related to the prognosis, immune regulation, immune cell infiltration, tumor microenvironment, TMB, and MSI of many kinds of tumors." (PMID 35592314, 2022). "The carbohydrate-binding motif at the core of SPA17 may mediate intercellular adhesion and thus be involved in lymph node migration and invasion of tumor cells." (PMID 35592314, 2022). "Immunological studies also showed that, as a powerful CTA, SPA17 may be a novel target for various tumor immunotherapies in the future." (PMID 35592314, 2022). "However, the underlying mechanism of how puromycin, irinotecan, alkaloid 5182598, and other SPA17-related drugs affect the pan-cancer tumor microenvironments remains to be found." (PMID 35592314, 2022). "SPA17, tumor size and endocrine-therapy were independent factors related to disease-free survival." (PMID 31417875, 2019). "Our findings suggest a role for SPA17 in tumor metastasis and aggressiveness." (PMID 31417875, 2019). "Therefore, we hypothesized that SPA17 could be a powerful and promising biomarker in predicting tumor immunotherapy effects." (PMID 35592314, 2022). "To understand the role of SPA17 in predicting the efficacy of immune checkpoint inhibitor (ICI) therapy, we assessed the correlation between the expression of SPA17 and two well-known immunotherapy predictive biomarkers, tumor mutation burden (TMB) and microsatellite instability (MIS)." (PMID 35592314, 2022). "Therefore, we conducted a genetic alteration analysis of SPA17 in the TCGA Pancancer tumor samples." (PMID 35592314, 2022). "However, whether localization of SPA17-AKAP to a particular subcellular site will be enough for tumor development remains to be further explored." (PMID 31417875, 2019). "SPA17 has been reported to play a potential role in sperm-egg interactions; however, increased functionality of this protein induced immature acrosome reaction and tumor changes in cells, which might support our current findings." (PMID 27507061, 2016). "The examination indicated the hub genes in tumor samples, including GAGE2A, GAGE1, MAGEA9, CTAG1A, CTAG1B, and MAGEA1; and the hub genes in healthy ovarian tissue samples, including SPA17, MAGEC1, KDM5B, SSX4, and MAGEA9." (PMID 37835834, 2023). "Potency of these products targeting TAg VP-MCC could be further enhanced by including CD8+ T cells with alternative tumor specificities such as MAGE-A3, survivin, and SPA17 expressed by VP-MCC." (PMID 33362774, 2020). "In addition, FSIP1 can bind to and activate cancer/testis antigen proteins (including CABYR, SPA17, AKAP3, AKAP4, and ROPN1) in the fibrous sheath in tumor cells, in turn promoting cancer progression." (PMID 28086239, 2017).
tumor (continued). "The highly conserved N-terminal sequence of SPA17 and the presence of an A-kinase-anchoring protein (AKAP)-binding motif within this region suggest that SPA17 may function independently of protein kinase A (PKA) in tumor cells separate from the AKAP complex." (PMID 35592314, 2022).
cancer (5 papers, 2012 to 2024). A tumor composed of atypical neoplastic, often pleomorphic cells that invade other tissues. "Specifically, SPA17 was a risk factor for 15 types of cancer patients and a protective factor for 11 cancers." (PMID 35592314, 2022). "Gene Set Enrichment Analysis (GSEA) revealed the enriched cancer hallmarks associated with SPA17 expression." (PMID 35592314, 2022). "Gene Set Enrichment Analysis (GSEA) was used to search the associated cancer hallmarks with SPA17 expression in each cancer type." (PMID 35592314, 2022). "To excavate the biological processes associated with SPA17 expression in cancers, we performed differential expression analysis between the top 30% SPA17 expression subgroup and bottom SPA17 expression subgroup in each cancer type." (PMID 35592314, 2022). "We employed the TIMER2.0 database to show the landscape of SPA17 associated with various immune cell infiltrations, which were conducted in a variety of quantitative immune infiltration platforms in cancers." (PMID 35592314, 2022). "SPA17 was deeply involved in the occurrence and development of cancer, which led us to study further the role of SPA17 in the cancer-immune response and microenvironment." (PMID 35592314, 2022). "The results indicated that SPA17 expression was unbalanced in cancers, consistent with previous studies." (PMID 35592314, 2022). "These drugs have been used to prevent and treat several cancers in recent years, and the correlations between these components and SPA17 should be examined in further investigations." (PMID 35592314, 2022). "The OS, DFI, DSS, and PFI analysis results were highly consistent in cancer patients, revealing that SPA17 was significantly related to the prognosis of cancer patients." (PMID 35592314, 2022). "The results showed that SPA17 was highly correlated with the prognosis of most cancers except ESCA, MESO, READ, STAD, and UCS." (PMID 35592314, 2022). "Another important finding of our study was the SPA17 expression was highly correlated to the immune infiltration of cancers." (PMID 35592314, 2022). "First, the expression levels of SPA17 in pan-cancer were analyzed based on the GTEx and TCGA databases." (PMID 35592314, 2022). "In this study, we found SPA17 was a promising biomarker of pan-cancer prognosis, which effectively predicted the response to cancer immunotherapy." (PMID 35592314, 2022). "The univariate Cox regression and Kaplan–Meier method were used to determine the prognostic role of SPA17 in each cancer." (PMID 35592314, 2022). "We concluded that SPA17 predicts the prognosis and immunotherapy effects of cancers and is a potential immunotherapy target." (PMID 35592314, 2022). "To uncover the expression levels of SPA17 across cancers, we integrated the TCGA and GTEx databases to reflect the level of SPA17 mRNA expression in pan-cancer." (PMID 35592314, 2022). "The univariate Cox regression and Kaplan–Meier method were used to assess the prognostic role of SPA17 in pan-cancer." (PMID 35592314, 2022). "The limited expression of normal tissues makes SPA17 ideal for targeting immune infiltrating cells in cancers." (PMID 35592314, 2022). "SPA17 had a prognostic role in predicting the prognosis of cancers, but the roles were complicated and multifaceted across cancers." (PMID 35592314, 2022). "The results show that a higher SPA17 expression indicated a better prognosis and more sensitivity to anti-PD-L1 immunotherapy in the IMvigor210 cancer cohort." (PMID 35592314, 2022). "SPA17 was aberrantly expressed in most cancer types and exhibited prognosis predictive ability in various cancers." (PMID 35592314, 2022). "Based on the DEGs between the high and low-SPA17 subgroups, we performed GSEA analysis across 33 cancer types to evaluate the SPA17-associated cancer hallmarks." (PMID 35592314, 2022).
cancer (continued). "Considering the special role of SPA17 in cancers and its potential role in cancer immunity, we designed the pan-cancer analysis to investigate the aberrant expression, prognostic role, and immunotherapy predictive ability of SPA17 in various cancers." (PMID 35592314, 2022). "The results suggest that SPA17 was abnormally upregulated in ten cancer types and downregulated in eleven cancer types." (PMID 35592314, 2022). "TIMER2.0 was the main platform to investigate the immune cell infiltrations related to SPA17 in pan-cancer." (PMID 35592314, 2022). "This suggests we further explore why SPA17 was abnormally expressed in cancers and its role in the ROS pathway." (PMID 35592314, 2022). "Our results suggest that SPA17 was an effective biomarker for predicting the response to blocking treatment at immune checkpoints in various cancers." (PMID 35592314, 2022). "This is consistent with the gene set enrichment analysis (GSEA) results showing positive correlations between SPA17 expression and the ROS pathway in cancers." (PMID 35592314, 2022). "This information prompts us to consider the role of SPA17 in cancer immunology." (PMID 35592314, 2022). "Finally, two independent cancer cohorts consisting of patients that received immune checkpoint blockade (ICB) therapy were used to examine the predictive role of SPA17 in cancer patient prognosis and immunotherapy response." (PMID 35592314, 2022). "However, the biological functions and clinical implications of SPA17 in cancers are still unclear and need to be further clarified." (PMID 35592314, 2022). "Next, we evaluated the relationship between SPA17 and the clinical prognosis of cancer patients." (PMID 35592314, 2022). "Our results suggest that SPA17 could have the power to predict the efficacy of ICIs in corresponding cancers." (PMID 35592314, 2022). "Clinically, SPA17 not only acted as a potent prognostic factor to predict the clinical outcomes of cancer patients but was also a promising immunotherapy predictive biomarker for cancer patients treated with immune-checkpoint inhibitors (ICIs)." (PMID 35592314, 2022). "Further investigation should focus on the function of the SPA17 protein in cancer cells." (PMID 35592314, 2022). "In summary, these results provide evidence that the abnormal expression of SPA17 may be involved in the immune response of cancers." (PMID 35592314, 2022). "Finally, specific inhibitors, like irinotecan and puromycin, which correlate with SPA17 expression in different cancer types, were also screened using Connectivity Map (CMap)." (PMID 35592314, 2022). "Given the abnormal SPA17 expressions observed in the cancers, we speculated if genetic alterations of SPA17 resulted in this phenomenon." (PMID 35592314, 2022). "Furthermore, oxidative phosphorylation, MYC targets, E2F targets, and androgen response were also closely related to the expression of SPA17 in cancers." (PMID 35592314, 2022). "However, because of our detailed results, further investigations of the predictive role of SPA17 in cancer immunotherapy need to be performed clinically and mechanically in individual cancer types." (PMID 35592314, 2022). "Multiple immune cell infiltration quantitative methods, including CIBERSORT, XCELL, MCPCounter, EPIC, and TIDE, were used to quantify the cell infiltration levels of each cancer sample and calculate the correlations between immune cells infiltration and SPA17 expression in each cancer." (PMID 35592314, 2022). "In addition, the correlation analysis between SPA17 and the pan-cancer immunomodulatory factors suggests that the SPA17 expression was highly correlated to the expression of specific immunomodulatory genes, especially in ACC, BRCA, LGG, THCA, THYM, and UVM." (PMID 35592314, 2022).
cancer (continued). "Furthermore, recent studies have shown that the inflammatory response, TNFA-signaling via NFKB, the IFN-α response, and the IFN- γ response were closely related to the immunotherapy and prognosis of cancer, providing a direction for further exploration of the role of SPA17 in tumors." (PMID 35592314, 2022). "Thus, why SPA17 is unevenly expressed in cancers is unsolved." (PMID 35592314, 2022). "According to our analysis, the deep deletion of SPA17 resulted in a lower SPA17 expression in patients with TGCT, although few genomic alterations were found in other cancer types." (PMID 35592314, 2022). "The most exciting finding was that SPA17 could significantly predict anti-PDL1 and anti-PD1 therapy responses in cancer patients." (PMID 35592314, 2022). "Recently, studies have found that SPA17 regulates the progression of various cancers, but its role in cancer immunotherapy is not clear." (PMID 35592314, 2022). "In general, SPA17 was positively correlated with the level of immune infiltration of many kinds of infiltrating cells, such as MDSC, progenitors of lymphoid, CD8+ T cell, and CD4+ T cell in various cancers." (PMID 35592314, 2022). "SPA17 is not expressed in normal tissues except in the testis and ciliated cells, but it is activated in malignant tumors." (PMID 35592314, 2022). "Most of these processes were significantly enriched in the cancer subgroups with high SPA17 expression; however, this was not true for BLCA, BRCA, OV, PAAD, THCA, and THYM." (PMID 35592314, 2022). "Similarly, testis-restricted targets such as SPA17, TEX14, LAMA1, SMOC1, TNFAIP6, GPC2, and COL20A1 may also be leveraged for their cancer-specificity." (PMID 38702309, 2024).
SPA17 also shares sentences with these, for which no sentence is quoted: ciliopathies (1 paper); ductal breast carcinoma in situ (1); esophageal squamous cell carcinoma (1); non-small cell lung carcinoma (1); Pan (1); T-cell lymphomas (1); teratozoospermia (1); thyroid carcinoma (1); triple-negative breast carcinoma (1).